WNT10A (Wnt family member 10A)
Diseases named in the same sentence as WNT10A in open-access papers (continued):
Sharing a sentence is not in itself a finding about the gene and the disease.
colorectal cancer (6 papers, 2018 to 2024). A primary or metastatic malignant neoplasm that affects the colon or rectum. "Wnt10A expression is related to tumour staging and plays a carcinogenic role in the biological process of colorectal cancer." (PMID 33417298, 2021). "For example, WNT10A was expressed in multiple tumors such as lung cancer, colorectal cancer, head and neck cancer, stomach cancer, pancreatic cancer, urothelial cancer, cervical cancer, and endometrial cancer." (PMID 32434423, 2020). "The only other known tumor entity characterized by WNT6/WNT10A overexpression are colorectal carcinomas and it is assumed that their mode of proliferation is linked to differential beta-catenin expression—as opposed to PTSMTs." (PMID 29881541, 2018). "For instance, epigenetic inactivation of SERP genes allowed constitutive Wnt signaling pathway in colorectal cancer, while overexpression of Wnt genes (Wnt 3, Wnt5b, Wnt6, Wnt10a, Wnt14, and Wnt16) activated Wnt signaling pathway in Chronic lymphocytic leukemia." (PMID 32904598, 2020).
Nail dystrophy (5 papers, 2016 to 2022). Onychodystrophy (nail dystrophy) refers to nail changes apart from changes of the color (nail dyschromia) and involves partial or complete disruption of the various keratinous layers of the nail plate. "Most individuals with pathogenic WNT10A variants underlying OODD or SSPS displayed characteristic nail dystrophies (six males and nine females; 94%), one infant with numerous missing teeth and moderate skin issues had normal nails." (PMID 36421794, 2022). "EDAR and EDARADD mutations would cause a clinically indistinguishable phenotype, but are inherited as autosomal, and WNT10A also causes a distinct phenotype with nail dystrophy." (PMID 30397018, 2019). "Approximately 20% of epithelial Wnt10a mutants also displayed defects in nail growth, consistent with onychodystrophy in human patients." (PMID 28589954, 2017).
ovarian carcinoma (5 papers, 2020 to 2025). A malignant neoplasm originating from the surface ovarian epithelium. "Clinicopathological association analysis revealed that Wnt10a was significantly associated with high-grade and late-stage ovarian cancer, which suggested that Wnt10a serves an oncogenic role during the carcinogenesis and progression of ovarian cancer." (PMID 36605938, 2022). "High expression of Wnt10A is associated with high tumour grade and advanced stage in patients with ovarian cancer and may be a predictor of patient survival." (PMID 33417298, 2021). "WNT10A expression correlates with advanced disease stage, higher tumor grade, and significantly lower five-year survival rates, supporting its oncogenic function in ovarian cancer." (PMID 41465326, 2025).
renal cell carcinoma (5 papers, 2012 to 2022). "WNT10A siRNA knockdown decreased cell proliferation and aggressiveness of renal cell carcinoma (RCC), and WNT10A acts as an autocrine oncogene both in RCC carcinogenesis and progression by activating WNT/β-catenin signaling." (PMID 36605938, 2022). "In contrast to PTSMT, it has been shown in renal cell carcinoma that WNT10A is involved in canonical WNT/beta-catenin signaling." (PMID 29881541, 2018). "Wnt10A plays an oncogenic role in renal cell carcinoma by activating the canonical Wnt pathway, and has been found to be highly expressed especially in the invasive fronts of esophageal cancer." (PMID 26646695, 2015).
acne (4 papers, 2018 to 2024). An inflammatory process of the sebaceous glands which is characterized by comedones, nodules, papules and/or pustules on the skin. "The missense allele (p.F228I) in WNT10A has a frequency of 0.03 in the control population and exerts a protective effect on acne." (PMID 30542056, 2018).
androgenetic alopecia (4 papers, 2014 to 2025). "This phenomenon is also observed in human androgenetic alopecia, consistent with identification of a WNT10A variant associated with lower expression levels and male pattern baldness." (PMID 28589954, 2017). "A Wnt10A deficiency causes deregulation of the hair cycle by shortening the anagen phase, which is observed in androgenetic alopecia hair follicles." (PMID 25299961, 2014). "A recent study demonstrated that Wnt10A, which is a member of the Wnt family, is involved in the etiology of androgenetic alopecia." (PMID 25299961, 2014).
endometrial cancer (4 papers, 2020 to 2023). Primary or metastatic malignant neoplasm involving the endometrium (mucous membrane that lines the endometrial cavity). "As observed from the results of the model, the risk score has the greatest influence on predicting the survival outcome, indicating that the risk model based on the WNT2 and WNT10A genes can better predict the prognosis of endometrial cancer." (PMID 34565373, 2021). "The WNT-10A and WNT-10B ligands have been associated with estrogen-related carcinogenesis of endometrial cancer." (PMID 37176048, 2023). "In addition to WNT7A, the expression of WNT10A and WNT10B ligands has been associated with estrogen-related carcinogenesis of endometrial cancer." (PMID 34068065, 2021). "However, the significance of the WNT10A gene in endometrial cancer, aside from its upregulated expression, remains unknown." (PMID 34068065, 2021).
gastric cancer (4 papers, 2010 to 2023). A primary or metastatic malignant neoplasm involving the stomach. "In gastric cancer, Helicobacter pylori upregulates the expression of Wnt10a and Wnt10b, thereby activating the Wnt/β-catenin pathway." (PMID 37608794, 2023). "WNT10A was significantly upregulated in two out of eight basic gastric cancers and one out of seven primary rectal tumors." (PMID 37685980, 2023). "A careful examination of the double stained tissues showed marked increase of WNT10A positive fibroblastic cells in scirrhous type gastric cancer which is a representative cancer with hyperplastic stroma." (PMID 21203463, 2010).
Chronic lymphocytic leukemia (3 papers, 2020 to 2021). "Wnt members, including Wnt3, Wnt4, Wnt5B, Wnt6, Wnt7B, Wnt9A, Wnt10A, Wnt14 and Wnt16, are highly expressed in chronic lymphocytic leukaemia B cells." (PMID 33417298, 2021). "In an Eμ-TCL1 mouse model of chronic lymphocytic leukemia, it was described that Wnt16, Wnt10a, Fzd1 and Fzd6 are pronounced increased in CD5+ B cells." (PMID 33659046, 2021).
melanoma (3 papers, 2019 to 2023). A malignant, usually aggressive tumor composed of atypical, neoplastic melanocytes. "Among them, WNT3 and WNT4 were implied as melanoma tumor suppressors; WNT7A and WNT10A displayed contribution to the female reproductive system adenocarcinomas." (PMID 35850748, 2022).
Obesity (3 papers, 2012 to 2021). Accumulation of substantial excess body fat. "In another study, disruption of circadian clocks in mice results in increased adipogenesis and obesity through silencing the canonical Wnt10a pathway, indicating the protective role of Wnt10a in the development of obesity." (PMID 34042263, 2021). "In this vein, the relationship of WNT proteins to adipose tissue is exemplified by WNT10a, which suppresses adipocytes differentiation and inhibits obesity in genetically obese mice." (PMID 23300646, 2012). "Future studies are warranted to determine whether obesity-related factors such as pro-inflammatory cytokines can increase the promoter methylation of Wnt10a, resulting in diminished capacity of MSCs to become osteoblasts and leading to osteoporosis." (PMID 27136753, 2016).
autosomal recessive ectodermal dysplasia (2 papers, 2010 to 2024). "The inducible expression of Wnt genes, including WNT10A, stimulates the proliferation of hepatic progenitor cells, and mutations in WNT10A are associated with an autosomal recessive ectodermal dysplasia." (PMID 21203463, 2010).
Clouston syndrome (2 papers, 2017 to 2022). Clouston syndrome (or hidrotic ectodermal dysplasia) is characterized by the clinical triad of nail dystrophy, alopecia, and palmoplantar hyperkeratosis. "The nail phenotype may be rather specific like in patients with Clouston syndrome or show a wider spectrum of nail plate abnormalities as observed in children with WNT10A or TP63 mutations." (PMID 36421794, 2022). "Hidrotic ectodermal dysplasia (ED) with the WNT10A mutation produces variable dentofacial symptoms." (PMID 29403230, 2017).
hypohidrosis (2 papers, 2017 to 2021). diminished sweating in response to appropriate stimuli. "We used targeted next generation sequencing to study EDA, EDAR, EDARADD, and WNT10A genes in 45 Egyptian ED patients with or without hypohidrosis." (PMID 34573371, 2021).
Infertility (2 papers, 2018 to 2022). "Our results demonstrated that the uterine weight was lower and endometrium became thinner, with no significant changes of β-catenin expression in the uterus of Wnt10a KO mice, suggesting postpubertal endometrial dysfunction and infertility." (PMID 35582421, 2022). "We generated WNT10A–/–mice, displaying a range of unique phenotypes of morpho/organogenetic failure, such as growth retardation, alopecia, kyphosis and infertility, and then focused on the functions of WNT10A in wound healing." (PMID 29596490, 2018). "First, under basal condition, WNT10A–/–mice uniquely showed various phenotypes of morpho/organogenetic failure, such as growth retardation, alopecia, kyphosis and infertility, in a background of osteogenetic and follicle growth failure." (PMID 29596490, 2018). "Collectively, our WNT10A–/–mice showed a range of unique phenotypes of morpho/organogenetic failure, including growth retardation, alopecia, kyphosis and infertility, in a background of essentially stromagenic failure, including osteogenetic and follicle growth failure." (PMID 29596490, 2018). "Furthermore, female homozygous WNT10A–/–mice showed a phenotype of infertility, since the tissue of the WNT10A–/–ovaries histopathologically had no or markedly fewer follicles than the ovaries in WT mice." (PMID 29596490, 2018).
keratoconus (2 papers, 2020 to 2026). A degenerative, structural disorder of the eye, characterized by a cone-shaped protrusion of the cornea. "WNT10A has been implicated by genetic association studies linking an exonic variant to keratoconus risk through reduced central corneal thickness, with additional pathway-level evidence supporting a role for Wnt signaling dysregulation in keratoconus." (PMID 41595486, 2026). "Meanwhile, genes in the Wnt signaling pathway have gained attention: one study found that polymorphisms in WNT10A and WNT7B were associated with keratoconus and central corneal thickness, dovetailing with transcriptomic evidence of Wnt pathway dysregulation in KC corneas." (PMID 41595486, 2026).
keratoderma (2 papers, 2017 to 2019). "Unexpectedly, in addition to directing normal embryonic tooth morphogenesis and adult progenitor cell proliferation, we find that WNT10A is required for region-specific differentiation, explaining the smooth tongue and palmoplantar keratoderma phenotypes observed in patients with WNT10A mutations." (PMID 28589954, 2017).
osteoporosis (2 papers, 2016 to 2020). A condition of reduced bone mass, with decreased cortical thickness and a decrease in the number and size of the trabeculae of cancellous bone (but normal chemical composition), resulting in increased fracture incidence. "For example, Wnt6 is expressed during long bone development, whereas the expression level of Wnt10a was also revealed downregulated in Runx2 knockout mice, as well as bone marrow MSCs isolated from ovariectomy-induced osteoporosis mice." (PMID 32829178, 2020).
Pulp calcification (2 papers, 2015 to 2023). Pulp calcifications may appear as punctate calcifications, irregular, roughly spherical mineralized masses in any part of the pulp. "In our WNT10A families, pulp stones were only observed in our oldest proband (age 28; family 6)." (PMID 25629078, 2015).
thyroid cancer (2 papers, 2022 to 2023). "In fact, WNT10A/beta-catenin pathway activation has been demonstrated to promote cellular characteristics of aggressiveness, such as proliferation and migration in thyroid cancer." (PMID 37208504, 2023). "The research group searched the GEPIA database and found that WNT10A was correlated with the survival prognosis of patients with thyroid cancer." (PMID 36605938, 2022).
acute lymphoblastic leukemia (1 paper, 2020). Leukemia with an acute onset, characterized by the presence of lymphoblasts in the bone marrow and the peripheral blood. "Other Wnts such as Wnt4, Wnt5B, Wnt6, Wnt7B, Wnt9A, Wnt10A, Wnt14, and Wnt16 are robustly expressed in CLL B-cells and acute lymphoblastic leukemia (ALL) cells, whereas these can be scarcely detected in normal pre-B cells." (PMID 33126517, 2020).
alopecia (1 paper, 2018). Hair loss usually from the scalp. "Under basal conditions, morphological examinations between the two groups of 12-week-old mice showed that WNT10A–/–mice were grossly smaller in size than WT mice and had overt alopecia and kyphosis." (PMID 29596490, 2018).
angioleiomyoma (1 paper, 2018). A benign, slow-growing neoplasm that arises from the dermis or subcutaneous tissue. "Only six genes show significant differences between the angioleiomyoma types (ISL1, NCSTN, TCF7, WNT10A, WNT11, WNT7A) but their relative expression levels were very low, which indicates no biological relevance (< 0.4 compared to standardized reference gene index)." (PMID 29881541, 2018).
anodontia (1 paper, 2024). Anodontia is an extreme developmental dental anomaly characterized by the complete absence of all teeth. "It is worth noting that patients with biallelic WNT10A loss-of-function variants showed anodontia in permanent dentition but almost normal deciduous dentition, indicating that WNT10A is crucial for permanent tooth development." (PMID 39408781, 2024).
Anxiety (1 paper, 2022). Intense feelings of nervousness, tension, or panic often arise in response to interpersonal stresses. "Our findings provided evidence that Wnt10a-/- mice exhibited spatial memory impairment and anxiety-like behavior." (PMID 35884806, 2022). "Neurobehavioral tests revealed that Wnt10a-/- mice exhibited spatial memory impairment and anxiety-like behavior." (PMID 35884806, 2022). "In the present study, we confirmed that Wnt10a-/- mice showed hippocampus-dependent spatial memory impairment and anxiety-like behavior." (PMID 35884806, 2022). "The results of the open field test exhibited a significant decrease in the total distance moved, the number of entries into the central area, and the time spent in the center of the box in Wnt10a-/- mice, indicating anxiety-like behavior." (PMID 35884806, 2022). "The findings of the open field test showed that the total distance moved, the number of entries into the central area, and the time spent in center of the box were significantly decreased in Wnt10a-/- mice compared with WT mice, indicating anxiety-like behavior." (PMID 35884806, 2022).
asthma (1 paper, 2024). "Single gene GSEA analysis revealed that HORMAD2, WNT10A, ATP6V1E2, CMBL, ARRDC4, and LPIN2 were primarily involved in Allograft rejection, Arginine biosynthesis, Asthma, and Fatty acid biosynthesis." (PMID 40635857, 2024).
basal cell carcinoma (1 paper, 2021). A carcinoma involving the basal cells. "KEGG analysis also highlights several pathways associated with disease including “basal cell carcinoma” (Wnt6, Gli2, Wnt10a) and “htlv-i infection” (Smad4, Wnt10a, Prkacb, Wnt6, Tgfbr2) in M. spretus." (PMID 34794440, 2021).
chronic kidney disease (1 paper, 2014). Impairment of the renal function secondary to chronic kidney damage persisting for three or more months. "WNT10A expression in kidney tissues obtained from AIN patient biopsies was much higher than that of samples from chronic kidney disease patients." (PMID 25054240, 2014). "In contrast to AIN tissue, WNT10A hardly expressed in kidney of chronic kidney disease." (PMID 25054240, 2014).
cleft lip (1 paper, 2024). Congenital defect in the upper lip where the maxillary prominence fails to merge with the merged medial nasal prominences. "Eight significant variants associated with craniofacial malformations such as non-syndromic cleft lip and palate, mandibular prognathism, ocular abnormalities, and tooth defects are found in AXIN2, BMP2, BMP4, NOTCH3, PTCH1, SOX10, and WNT10A." (PMID 38785976, 2024).
colitis (1 paper, 2022). Inflammation of the colon. "Western blot analysis of the colon samples for Wnt6 and Wnt10a expression confirmed a reduction in these two proteins in colitis mice, which was rescued by BBR." (PMID 36528592, 2022).
colon cancer (1 paper, 2015). "Here, we validated that Wnt pathway genes such as DKK-1, DVL-1 and Wnt10A are indeed positively regulated by Fra-1 in both HT29 and HCT15 colon cancer cell lines." (PMID 26646695, 2015).
diabetic kidney disease (1 paper, 2022). Progressive kidney disorder caused by vascular damage to the glomerular capillaries, in patients with diabetes mellitus. "Based on the results of transcriptomics, the pathogenesis of diabetic kidney disease may involve 11 candidate differential genes: Egr1, Foxo3, Pik3r3, Fgf1, Sost, Wnt10a, Tgif2, Akt2, Mep1b, Col1a1, Apoe." (PMID 36249745, 2022).
diabetic neuropathy (1 paper, 2021). A chronic, pathological complication associated with diabetes mellitus, where nerve damages are incurred due to diabetic microvascular injury involving small blood vessels that supply these nerves, resulting in peripheral and/or autonomic nerve dysfunction. "However, Wnt10a and mediated canonical Wnt signalling are also induced in spinal cord of diabetic rat, and dexmedetomidine treatment could alleviate diabetic neuropathy pain by inhibiting the canonical Wnt10a pathway." (PMID 34042263, 2021).
female infertility (1 paper, 2022). Diminished or absent ability of a female to achieve conception. "Together, our findings indicate that deficiency of Wnt10a causes female infertility through β-catenin and Cyp19a1signaling pathways in mice." (PMID 35582421, 2022).
hypophosphatasia (1 paper, 2024). Hypophosphatasia (HPP) is a rare heritable metabolic disorder characterized by defective mineralization of bone and/or teeth in the presence of reduced activity of unfractionated serum alkaline phosphatase (ALP). "In Case 2, the variant described for hypophosphatasia was identified, and a variant of uncertain significance was additionally identified in the WNT10A gene." (PMID 39519277, 2024).
liver fibrosis (1 paper, 2019). "In another study, it was found that miR-378a-3p could inhibit the activity of hepatic stellate cells (HSCs) through the signaling pathway of Wnt/β-Catenin by targeting Wnt10a; miR-29a could alleviate liver fibrosis through regulation of the signaling of Wnt/β-Catenin." (PMID 31178968, 2019).
lung adenocarcinoma (1 paper, 2020). A carcinoma that arises from the lung and is characterized by the presence of malignant glandular epithelial cells. "WNT10A, PDGFA, TNF, and NRG1 had been identified as important paracrine factors from infiltrated dendritic cells to regulate neuropathic pain associated with lung adenocarcinoma." (PMID 32434423, 2020). "TNF, WNT10A, PDGFA, and NRG1 derived from infiltrated dendritic cells in lung adenocarcinoma microenvironment were proved to worsen neuropathic pain associated with cancers by sensitizing sensory neurons." (PMID 32434423, 2020).
pancreatic ductal adenocarcinoma (1 paper, 2026). An infiltrating adenocarcinoma that arises from the epithelial cells of the pancreas. "In pancreatic ductal adenocarcinoma (PDAC), elevated WNT7B and WNT10A correlate with aggressive, basal-like disease and poor patient survival, but the mechanisms underlying this association remain unclear." (PMID 41797924, 2026).